FGF19 (fibroblast growth factor 19)
Diseases named in the same sentence as FGF19 in open-access papers (continued):
Sharing a sentence is not in itself a finding about the gene and the disease.
hyperlipidemia (5 papers, 2013 to 2022). "By avoiding enterohepatic circulation, cilofexor primarily targets intestinal FXR receptors to stimulate fibroblast growth factor 19 (FGF19) release while avoiding systemic side effects such as pruritus, hyperlipidemia, and hepatotoxicity." (PMID 36613602, 2022). "FGF19 also attenuated HFD‐induced hyperlipidaemia by reducing TG and TC levels." (PMID 33751819, 2021). "FGF19 not only reduced HFD‐induced body weight gain, excessive lipid accumulation and hyperlipidaemia but also promoted energy expenditure (PGC‐1α, UCP‐1, PPAR‐γ) in brown adipose tissue (BAT)." (PMID 33751819, 2021).
hypothyroidism (5 papers, 2016 to 2025). Abnormally low levels of thyroid hormone. "Since the association between FGF19 and hypothyroidism is still unclear, our study aims to provide more evidence for people to understand the potential role of FGF19 in hypothyroidism." (PMID 27684859, 2016). "However, the underlying mechanism by which FGF-19 induces hyperlipidemia in patients with hypothyroidism is not yet fully understood." (PMID 39015803, 2024). "An observational study has also indicated that circulating FGF19 levels are reduced in individuals with hypothyroidism and subclinical hypothyroidism." (PMID 40072746, 2025). "Serum FGF-19 levels were increased in patients with hypothyroidism and were correlated with circulating TSH levels." (PMID 39015803, 2024). "Regarding FGF19, an endocrine hormone regulating various metabolic processes, its decreased level was reported in the sera of patients with overt hypothyroidism and subclinical hypothyroidism; however, its role in autoimmunity is unclear." (PMID 39744635, 2024). "Consistent with this notion, circulating FGF-19 concentrations significantly increased in patients with hypothyroidism which was independently correlated with serum concentrations of thyroid-stimulating hormone." (PMID 34784265, 2022). "Compared with the healthy control, the present study revealed that serum FGF19 levels were significantly decreased in overt hypothyroidism patients (78.7 [52.7–121.2] vs 292.4 [210.2–426.5] pg/mL, P <0.001)." (PMID 27684859, 2016). "Further studies are needed to elucidate the role of FGF19 in the development of hypothyroidism and its bridging function in the connection of thyroid dysfunctions and metabolic diseases." (PMID 27684859, 2016). "Further studies are needed to elucidate the role of FGF19 in the development of hypothyroidism." (PMID 27684859, 2016). "In conclusion, thyroid insufficiency but not thyroid autoimmunity may have impacted serum FGF19 concentrations." (PMID 27684859, 2016). "Therefore, it seems that thyroid insufficiency but not thyroid autoimmunity may have an impact on serum FGF19 concentrations." (PMID 27684859, 2016).
Impaired glucose tolerance (5 papers, 2013 to 2024). An abnormal resistance to glucose, i.e., a reduction in the ability to maintain glucose levels in the blood stream within normal limits following oral or intravenous administration of glucose. "Considering the glucose- and insulin-lowering actions of FGF19 and/or FGF21 in diabetic rodents, the potential of FGF19 and/or FGF21 treatment to ameliorate impaired glucose tolerance and insulin resistance in GDM patients warrants future attention." (PMID 24260557, 2013).
melanoma (5 papers, 2019 to 2024). A malignant, usually aggressive tumor composed of atypical, neoplastic melanocytes. "TRAF6 in melanoma cells regulates the secretion of FGF19 through the NF-κB pathway, which activates CAFs to facilitate the malignant phenotype." (PMID 39759028, 2024). "In melanoma cells, TRAF6 promotes nuclear factor kappa-light-chain-enhancer of activated B cells (NFkB)-dependent release of fibroblast growth factor 19 (FGF19), implicated in the transformation and activation of fibroblasts." (PMID 33036192, 2020). "FGF19-mediated CAFs’ activation supports, in turn, the malignant and invasive phenotype of melanoma cells and their drugs resistance." (PMID 33036192, 2020). "Furthermore, TRAF6 has been shown to support the malignant phenotype of melanoma cells by activating the NF-κB/FGF19 signaling pathway." (PMID 36010884, 2022). "Genomic profiling of 23 available subjects also identified gene amplifications of cell cycle regulators (Cyclin D1, CDK4, or CDK6), fibroblast growth factors (FGF19, FGF3, and FGF4) and EMSY (a DNA repair inactivating gene) uniquely clustered in acral melanoma subjects in the study." (PMID 30642373, 2019).
nasopharyngeal carcinoma (5 papers, 2022 to 2026). A carcinoma arising from the nasopharyngeal epithelium. "MSCs-EVs molecules have been shown to transfer FGF19 to nasopharyngeal cancer cells, in turn, activating a FGF19-FGFR4-dependent ERK signaling pathway that stimulates cancer cell proliferation and migration." (PMID 35842634, 2022). "In addition, it was found that FGF-19 enhances angiogenesis in nasopharyngeal carcinoma by preventing tripartite motif containing 21 (TRIM21)-mediated Annexin II degradation, thereby increasing VEGF expression." (PMID 40232500, 2025). "In nasopharyngeal carcinoma (NPC), FGF19 is overexpressed, promoting angiogenesis and tumor progression, making it a potential non-invasive biomarker for early diagnosis and treatment." (PMID 41328353, 2026). "It was found that the isolated BM-MSC-EVs significantly regulate fibroblast growth factor-19 (FGF-19); they therefore act as a potent regulators of nasopharyngeal carcinoma cell lines (CNE1, CNE2, 5-8F and 6-10B) via the FGF19-FGFR4-dependent ERK signalling cascade and by modulating EMT." (PMID 39120301, 2024).
Sepsis (5 papers, 2022 to 2024). Sepsis is defined as life-threatening organ dysfunction caused by a dysregulated host response to infection. "In this study, FGF19 was associated with abnormal GI function in patients with sepsis, which provides a new perspective for the assessment of GI dysfunction." (PMID 39296513, 2024). "In conclusion, serum FGF19 is a risk factor for sepsis combined with GI dysfunction, and the serum FGF19 level at ICU admission can be used as a novel biomarker to predict and evaluate the risk of GI dysfunction in sepsis patients during their ICU stay." (PMID 39296513, 2024). "The detailed mechanism by which 9-Hydroxystearate reduces sepsis risk via FGF-19 and IL-2 requires further investigation." (PMID 39205680, 2024). "The IVW analysis revealed a notable inverse association between FGF-19 and sepsis (OR = 0.751, 95% CI (confidence interval) = 0.598–0.944)." (PMID 39205680, 2024). "Serum FGF19 concentrations above 210 μg/mL indicate an increased risk of GI dysfunction in patients with sepsis." (PMID 39296513, 2024). "In our study, we found that the association of 9-hydroxystearate levels with increased FGF-19 correlated with a reduced sepsis risk, contributing 9.436% to the protective effect of 9-hydroxystearate." (PMID 39205680, 2024). "We previously reported that serum FGF19 level was decreased in patients with sepsis-associated gastrointestinal dysfunction." (PMID 35847588, 2022). "Similarly, 9-hydroxystearate’s association with increased FGF-19 and decreased IL-2 correlated with a reduced sepsis risk, contributing 9.436% and 12.565% respectively to the protective effect of 9-hydroxystearate." (PMID 39205680, 2024). "Additionally, 9-Hydroxystearate exhibited a dual protective role against sepsis, positively associated with FGF-19 and negatively with IL-2, contributing 9.436% and 12.565% respectively to its protective effect." (PMID 39205680, 2024). "Accordingly, we hypothesized that increased FGF19 levels are associated with AGI development in sepsis patients, and the aim of this manuscript is performed to verify this hypothesis." (PMID 39296513, 2024). "In summary, FGF19 pretreatment mainly improved LPS-induced lipid metabolism, indicating FGF19 might be closely associated with improved metabolic disturbance of sepsis." (PMID 35847588, 2022). "Importantly, recent study proved that lipopolysaccharide (LPS) inhibited the expression of FGFR4 in the livers of mice, and our previous study elucidated the association between serum FGF19 level and sepsis-associated gastrointestinal dysfunction." (PMID 35847588, 2022). "However, it is largely unknown about the roles of FGF19 in improving sepsis-associated metabolic disorder and organ injury." (PMID 35847588, 2022). "Therefore, we speculated that FGF19 could be a key regulator of metabolism homeostasis and plays a protective role in sepsis-associated metabolic disorder and organ injury." (PMID 35847588, 2022). "This study revealed that in the early stage of sepsis, the serum FGF19 concentration in sepsis patients with GI dysfunction was almost three times greater than that in sepsis patients without GI dysfunction." (PMID 39296513, 2024). "Correlations of FGF19 levels with different clinical parameters and blood markers in sepsis patients." (PMID 39296513, 2024). "The significant correlations observed between piperine and AXIN1, as well as 9-hydroxyoctadecanoic acid and IL-2 and FGF-19, further support the intricate relationships between metabolites and inflammatory factors in the context of sepsis." (PMID 39205680, 2024). "Inflammatory factors such as AXIN-1, FGF-19, FGF-23, IL-4, and OSM were negatively causally associated with sepsis, while IL-2 was positively associated." (PMID 39205680, 2024). "The serum FGF19 level of sepsis patients with GI dysfunction was significantly greater than that of sepsis patients without GI dysfunction when admitted to the ICU [355.1 (37.2, 2315.4) pg./mL vs. 127.4 (5.7, 944.2) pg./mL, p = 0.003]." (PMID 39296513, 2024).
Sepsis (continued). "Receiver operating characteristic (ROC) analysis was used to determine the value of FGF19 in predicting GI dysfunction in patients with sepsis." (PMID 39296513, 2024). "The results showed that sepsis patients exhibited significantly elevated levels of the inflammatory factor IL-2 and significantly reduced levels of FGF-19 and AXIN1 compared to healthy controls." (PMID 39205680, 2024). "When the cutoff value of serum FGF19 was 210 μg/mL, the corresponding sensitivity was 78.3% and the specificity was 65.3%, suggesting that an increase in the serum FGF19 concentration was a significant predictor of sepsis combined with GI dysfunction." (PMID 39296513, 2024). "ROC curve analysis results showed that the area under ROC curve (AUC) of FGF19 in predicting sepsis complicated with GI dysfunction was 0.773 (95%CI 0.712–0.827)." (PMID 39296513, 2024). "In our study, we identified several inflammatory factors, including FGF-19, AXIN1, FGF-23, IL-4, OSM, and IL-2, that showed statistically significant associations with sepsis risk using the IVW method in MR analyses." (PMID 39205680, 2024). "When the cutoff value of serum FGF19 was 210 μg/mL, the sensitivity and specificity of predicting sepsis with GI dysfunction were 78.3 and 65.3%, respectively." (PMID 39296513, 2024). "In the future, the potential therapeutic values of NGM282 or other FGF19 analogue in sepsis should be conducted in a well-designed clinical trial." (PMID 35847588, 2022). "We believe that the apparent increase in FGF19 in sepsis patients with GI dysfunction may be due to Bile acid regulation failure and increased responsiveness to inflammation, and the specific mechanisms need to be further studied." (PMID 39296513, 2024). "Serum FGF19 could be considered as a novel predictor or biomarker of GI dysfunction in patients with sepsis." (PMID 39296513, 2024). "9-Hydroxystearate also exhibited a protective role against sepsis, mediated through its positive association with FGF-19 and negative association with IL-2, contributing 9.436% and 12.565%, respectively, to its protective effect." (PMID 39205680, 2024). "Serum FGF19 levels were significantly higher in patients with sepsis-associated GI dysfunction than in patients without GI dysfunction [355.1 (37.2, 2315.4) μg/mL vs. 127.4 (5.7, 944.2) μg/mL, p = 0.003]." (PMID 39296513, 2024). "We identified 36 metabolites significantly associated with sepsis (p < 0.05), with AXIN1, FGF-19, FGF-23, IL-4, and OSM showing an inverse association, suggesting a protective role, while IL-2 exhibited a positive correlation, indicating a potential risk factor." (PMID 39205680, 2024). "So, FGF19 could be potential metabolic regulator during sepsis and therapeutic target for sepsis treatment." (PMID 35847588, 2022). "Taken together, FGF19 alleviates LPS-induced organ injury associated with improved serum LA and GLA levels and oxidative stress, suggesting that FGF19 might be a promising target for metabolic therapy for sepsis." (PMID 35847588, 2022). "Considering the characteristic of intestine-derived, FGF19 could be a potential therapeutic target for sepsis from the view of FA regulation." (PMID 35847588, 2022). "Therefore, increased FGF19 levels might be an early predictor of acute gastrointestinal (AGI) dysfunction in sepsis patients." (PMID 39296513, 2024). "This study also revealed that the FGF19 level was positively correlated with the SOFA score and APACHE II score in sepsis patients with GI dysfunction." (PMID 39296513, 2024). "Experimental validation confirmed significantly elevated IL-2 levels and reduced FGF-19, AXIN1, piperine, and 9-hydroxyoctadecanoic acid levels in sepsis patients compared to healthy controls." (PMID 39205680, 2024). "In addition, the results of this study revealed that baseline serum concentrations of FGF19 were positively correlated with baseline concentrations of PCT, a typical inflammatory biomarker for sepsis." (PMID 39296513, 2024).
Sepsis (continued). "Efficacy analysis of serum FGF19 and PCT in predicting GI dysfunction in patients with sepsis." (PMID 39296513, 2024). "In this study, sepsis patients in the ICU of the Shanghai General Hospital from June 2023 to December 2023 were included to observe serum FGF19 level and explore the relationship between serum FGF19 level and GI dysfunction." (PMID 39296513, 2024). "However, in this study, both bile acid and FGF19 levels were elevated in sepsis patients with GI dysfunction, indicating that FGF metabolic axis did not play a decisive role in the changes of bile acid and FGF19 levels in patients with sepsis." (PMID 39296513, 2024). "This essential component of fibroblast growth factor (FGF) receptor complexes is required for high-affinity binding of endocrine FGF19 and FGF21 to evoke the signaling cascade actively involved in homeostatic maintenance of glucose metabolism and energy expenditure that are dysregulated in sepsis." (PMID 37638006, 2023).
thyroid cancer (5 papers, 2017 to 2026). "Future experiments are necessary to explore the causality between FGF19 and cancer further, to determine its potentials in therapeutic target for cancer, particularly thyroid cancer." (PMID 40072746, 2025). "The overexpression of FGF19 is significantly associated with tumor-distant metastasis in thyroid cancer." (PMID 28678795, 2017). "In TC cells, transfection with siRNA-FGF19 can significantly inhibit the expression of FGF19, thereby suppressing the migration and invasion of thyroid cancer cells." (PMID 41328353, 2026). "In our MR analysis, genetically predicted circulating levels of FGF19 have been identified as a protective factor for thyroid cancer." (PMID 40072746, 2025). "Additionally, there was a notable association between levels of FGF19, IL2RB, TNFRSF9, S100-A12, FLT3LG, and CCL19 and a decreased risk of thyroid cancer." (PMID 40072746, 2025). "Interestingly, a recent study focused on the role of FGF19/FGFR4/KLB signaling pathway in the development of thyroid cancers with upregulation of serum levels of KLB, FGF19, and FGFR4 in patients with thyroid cancer, compared to healthy controls." (PMID 31408968, 2019).
colitis (4 papers, 2020 to 2025). Inflammation of the colon. "Matrix metalloproteinase (MMP)-10, IL-17A, FGF-19, IL-10, and CXCL9 were increased in patients with exclusive colonic inflammation, that is, UC and colonic CD, compared to patients with exclusive ileal inflammation, that is, ileal CD." (PMID 39495605, 2025).
hepatoblastoma (4 papers, 2016 to 2026). Hepatoblastoma (HB) is a malignant hepatic tumor and is the most common pediatric liver cancer. "Through the analysis of primary tumor tissue samples from patients with hepatoblastoma, gene expression patterns associated with FGF19 have been precisely identified." (PMID 41328353, 2026). "Silencing the FGF19 gene using shRNA or neutralizing secreted FGF19 using anti-FGF19 antibodies can significantly inhibit the proliferation of hepatoblastoma cells, with this inhibitory effect being dose-dependent." (PMID 41328353, 2026). "Taken together, these findings indicate the heterogeneous expression of FGF19 in hepatoblastoma and underscore its role in tumor cell proliferation." (PMID 41328353, 2026). "Relevant studies have revealed significant transcriptional heterogeneity of FGF19 in hepatoblastoma, with its expression closely correlated with the activation of the Wnt signaling pathway." (PMID 41328353, 2026). "The high expression of FGF19 is closely related to the proliferative capacity of hepatoblastoma cells." (PMID 41328353, 2026). "The efficacy and safety of FGF19-targeted therapies, administered alone or in combination, ought to be evaluated in clinical trials, specifically in rare tumors including hepatoblastoma, DFSP GBM, and RMS." (PMID 41328353, 2026). "FGF19-producing cholangiocytic-like hepatoblastoma cells are characterized by high WNT/b-catenin signaling, a low proliferation rate, and expression of cholangiocyte markers KRT19 and SOX4, a transcription factor important in biliary-lineage differentiation." (PMID 40684183, 2025). "Nonetheless, our cohort shows that a significant proportion of primary hepatoblastomas exhibit FGF19 expression within the embryonal components." (PMID 39567523, 2024). "We next investigated the mechanism by which FGF19 expression is induced in hepatoblastoma cells using the FGF19-positive tumoroids." (PMID 39567523, 2024). "RNA expression analysis in hepatoblastoma tumors revealed that the high expression of FGF19 signaling pathway components as well as the low expression of FGF19 signaling repression targets correlates with the aggressiveness of the tumors." (PMID 27382436, 2016). "To dissect the cytokine signaling in hepatoblastoma, we used secretome proteomics to analyze the proteins secreted from Hep293TT cells and identified the specific secretion of FGF19." (PMID 27382436, 2016). "We determined that silencing FGF19 by shRNAs or neutralizing secreted FGF19 by anti-FGF19 antibody inhibits the proliferation of hepatoblastoma cells." (PMID 27382436, 2016). "In hepatoblastoma, FGF19 binds to the receptor, activating downstream signaling pathways." (PMID 41328353, 2026). "Additionally, the use of FGF receptor kinase inhibitors, such as LY2874455, can effectively inhibit the activation of the FGF19 signaling pathway, thereby suppressing the growth of hepatoblastoma cells." (PMID 41328353, 2026). "We next interrogated the correlation of FGF19 expression in primary hepatoblastoma tissues with the proliferative index and pattern of β-catenin staining, where nuclear β-catenin indicates high levels of Wnt signaling, while normal hepatocytes exhibit primarily membrane-bound β-catenin." (PMID 39567523, 2024). "Thus, these FGF19-positive hepatoblastoma tumoroids depended on the endogenous expression of FGF19 and subsequent signaling through FGFR4 and MAPK." (PMID 39567523, 2024). "Although embryonal hepatoblastoma cells can bypass the requirement for exogenous growth factors through the expression of FGFs, including FGF19, our studies suggest that a significant portion of hepatoblastoma cells do not proliferate in the absence of growth factors from cell-extrinsic sources." (PMID 39567523, 2024).